RB1 (RB transcriptional corepressor 1)
Diseases named in the same sentence as RB1 in open-access papers (continued):
Sharing a sentence is not in itself a finding about the gene and the disease.
bone sarcoma (2 papers, 2012 to 2023). A sarcoma that arises from the bone.
carcinosarcoma (2 papers, 2023 to 2025). A malignant tumor composed of a mixture of carcinomatous and sarcomatous elements.
cholangiocarcinoma (2 papers, 2022 to 2024). A carcinoma that arises from the intrahepatic biliary tree (intrahepatic cholangiocarcinoma) or from the junction, or adjacent to the junction, of the right and left hepatic ducts (hilar cholangiocarcinoma). "In cholangiocarcinoma, ASPH may promote cholangiocarcinoma progression by regulating RB1 phosphorylation." (PMID 35965520, 2022).
CNS embryonal tumor (2 papers, 2022 to 2025). "A biopsy was undertaken (resection was deemed high risk) and demonstrated a CNS embryonal tumor (WHO grade 4) with somatic mutations in retinoblastoma 1 (RB1) and mutY DNA glycosylase (MUTYH)." (PMID 35677741, 2022).
co-infection (2 papers, 2012 to 2023). "Here we have shown that primary infection of DF-1 cells with either rLS-RFP or rB1-GFP decreases the co-infection rates by the heterologous strain." (PMID 23034005, 2012).
colitis (2 papers, 2013 to 2025). Inflammation of the colon. "Rg1, Rg3, Rf, Rd, Re, and Rb1 have all been shown to alleviate colitis, but it is unclear which ginsenoside has the most prominent anti-inflammatory effect." (PMID 40227284, 2025).
colon adenocarcinoma (2 papers, 2022 to 2026).
Cowden disease (2 papers, 2021 to 2022). A genodermatosis characterized by the presence of multiple hamartomas in various tissues and an increased risk for malignancies of the breast, thyroid, endometrium, kidney and colorectum. "We excluded articles irrelevant to our query and reports of cases where underlying genetic or metabolic conditions associated with a high incidence of lipomatous tumors were present (e.g., Cowden syndrome, Cushing’s syndrome, Rb1 mutation, familial multiple lipomatosis, hamartoma tumor syndrome)." (PMID 36556917, 2022).
cutaneous squamous cell carcinoma (2 papers, 2016 to 2022).
diabetic cardiomyopathy (2 papers, 2023 to 2024). Diabetic cardiomyopathy is a disorder of the heart muscle in people with diabetes. "Numerous studies have demonstrated that Rb1 ameliorates diabetic cardiomyopathy and myocardial ischemia by inhibiting RyR2 activity to regulate calcium signaling." (PMID 38961333, 2024). "Another major finding of the present study is that phosphorylation RyR2 at S2808 by carbonylation oxidative stress is important mechanisms of diabetic cardiomyopathy; Rb1 and insulin treatment is more efficacious way to reduce the process of phosphorylation RyR2." (PMID 38961333, 2024). "Moreover, the present study establishes that the mechanism of Rb1 in diabetic cardiomyopathy involves ROS, RCS, and RyR2." (PMID 38961333, 2024).
diabetic kidney disease (2 papers, 2021 to 2025). Progressive kidney disorder caused by vascular damage to the glomerular capillaries, in patients with diabetes mellitus. "Rb1 can reduce the complications of diabetic nephropathy by reducing free fatty acids, promoting lipid metabolism, improving insulin resistance in obese mice, inhibiting the levels of TNF-a and IL-6 inflammatory factors, and the decomposition of adipocytes." (PMID 34512359, 2021). "Earlier research has indicated that Rb1 can alleviate urinary albumin elevation and renal tissue pathology in diabetic kidney disease (DKD) and unilateral ureteral obstruction (UUO)." (PMID 40682486, 2025).
ductal carcinoma in situ (2 papers, 2022).
Epstein-Barr virus infection (2 papers, 2007 to 2019). An infection that is caused by Epstein-Barr virus. "Further studies with larger series are needed to elucidate the influence of Epstein-Barr virus infection, frequency of Rb-1 gene loss and high expression of P21 on the clinical setting and the relationship of these three factors to treatment response in HD patients." (PMID 17625704, 2007).
esophageal neoplasms (2 papers, 2020 to 2021). "p16 overexpression in these highly malignant esophageal neoplasms is considered to represent the sequel of intracellular dysregulation of the RB1 signaling pathway and not HPV infection." (PMID 32556556, 2021). "p16 was therefore considered to be induced through an inactivation of the RB1 signaling pathway and not through HPV infection in highly malignant esophageal neoplasms." (PMID 32556556, 2021).
esophageal small-cell carcinoma (2 papers, 2020 to 2021). "In particular, p16 overexpression and loss of Rb1 protein were constantly detected in esophageal small-cell carcinomas." (PMID 32556556, 2021). "It has been reported that RB1 expression was downregulated in esophageal small-cell carcinoma." (PMID 32104700, 2020).
gastrointestinal stromal tumor (2 papers, 2020 to 2023). "In contrast, RB1 that was regarded as a tumor suppressor gene in gastrointestinal stromal tumors and was identified as a monotonically increasing gene, while three oncogenes including NFE2L2, ABL1, and LASP1 were identified as monotonically decreasing genes." (PMID 33273919, 2020).
Hyperinsulinemia (2 papers, 2014 to 2022). An increased concentration of insulin in the blood. "Plasma insulin was elevated in HF diet-induced obese mice, but Rb1 did not significantly reverse hyperinsulinemia in these animals." (PMID 24675731, 2014).
kidney cancer (2 papers, 2020 to 2025). Primary or metastatic malignant neoplasm involving the kidney. "Why RB1 loss does not occur in other cancers (e.g., kidney cancer) is less clear, however, since there is co-occurrence with deregulation of CDK4/6 activity the selective pressure may be limited." (PMID 32242058, 2020). "Besides, RB1 deletions have a negative effect on the treatment outcomes of multiple other cancer types, including kidney cancer and uterine corpus endometrial carcinoma (UCEC)." (PMID 40904703, 2025).
liver disease (2 papers, 2019 to 2023). "Looking at the most disparate amplifications or deletions resulted in distinct changes in liver disease such as RB1 deletions occurring at 25% of patients with little to no mutations were found in bone and just over 10% were found in lymph node." (PMID 36054271, 2023).
malignant nervous system tumors (2 papers, 2015 to 2025). "Hypermethylation of RB1 CpG island is a common epigenetic event associated with the development of malignant nervous system tumors." (PMID 25767620, 2015).
mammary adenocarcinoma (2 papers, 2004 to 2011).
mucinous carcinoma (2 papers, 2015 to 2021). "The co-expression of Rb1+ and ER+ was seen in 19 % of HGSC cases compared to 10, 6 and 5 % in LGSC, EC and mucinous carcinomas, respectively (p < 0.05)." (PMID 26043844, 2015).
mucosal melanoma (2 papers, 2019 to 2024). A melanoma that arises from a mucosal site. "RB1 (retinoblastoma 1) mutations occur in 4-15% of cutaneous, 9-17% of acral, and 0-21% of mucosal melanomas." (PMID 38469235, 2024).
myeloid malignancies (2 papers, 2013 to 2022). "The data indicate the presence of 2 distinct breakpoint cluster regions: centromeric of RB1 in myeloid malignancies and distal to RB1 in some lymphoid B-cell and T-cell malignancies." (PMID 24385774, 2013).
oral mucositis (2 papers, 2017 to 2024). Inflammation of the mucous membranes of any of the structures in the mouth. "We found that one germline SNP in RB1 (rs2227311, p-value = 0.034, OR = 0.67) showed a protective effect for oral mucositis." (PMID 28678827, 2017). "- SNP in RB1 (rs2227311, p-value = 0.034, OR = 0.67) showed a protective effect for oral mucositis." (PMID 38473311, 2024).
osteoarthritis (2 papers, 2015 to 2025). A noninflammatory degenerative joint disease occurring chiefly in older persons, characterized by degeneration of the articular cartilage, hypertrophy of bone at the margins and changes in the synovial membrane. "In another study, Rb1 showed promising effects in inhibiting MMP-13 expression and promoting type II collagen expression through regulation of the Notch signaling pathway in osteoarthritis." (PMID 40507179, 2025).
Parathyroid carcinomas (2 papers, 2020 to 2021). "Parathyroid carcinomas can also hyperexpress galanin‐3 and lose immunoreactivity to parafibromin and RB‐1." (PMID 32884778, 2020). "In short, while LOH of the RB1 locus seem to confer high sensitivity for the detection of parathyroid carcinoma, a significant amount of adenomas harbor the same genetic aberrancy, and the reduced specificity renders this marker of less value when screening for rare carcinomas in PHPT." (PMID 33269427, 2021). "Similarly, loss of the retinoblastoma 1 (RB1) gene, encoding pRB, is observed in the majority of parathyroid carcinomas, however inactivating mutations have not been reported." (PMID 33269427, 2021).
PEComas (2 papers, 2024).
pineal tumors (2 papers, 1997 to 2021). "A nonsense mutation in exon 17 (codon 556) of the RB1 gene was found to be present homozygously in both the retinal and the pineal tumours." (PMID 9400934, 1997).
progeria (2 papers, 2011 to 2014). "Cells from human progeria and muscular dystrophy patients have gene expression signatures that implicate central defects in RB1 activity as well." (PMID 21464947, 2011). "However, for progeria cells, a direct link to RB1 signaling has yet to be demonstrated." (PMID 21464947, 2011).
renal fibrosis (2 papers, 2025 to 2026). A final common manifestation of a wide variety of chronic kidney diseases characterized by glomerulosclerosis and tubulointerstitial fibrosis. "Rb1 exhibits beneficial therapeutic effects in promoting renal angiogenesis and alleviating renal fibrosis, but the mechanism of this renal repair remains incompletely elucidated." (PMID 40682486, 2025). "This study observed that Rb1 can effectively promote renal angiogenesis and alleviate renal fibrosis in mice transitioning from AKI to CKD by activating the AKT signalling pathway via targeting VEGFR2." (PMID 40682486, 2025). "Interestingly, our findings suggest that Rb1 can enhance renal angiogenesis and attenuate renal fibrosis of uIRI‐induced mice." (PMID 40682486, 2025). "Here, we discovered that Rb1 could alleviate kidney pathological damage in mice with unilateral ischaemia/reperfusion injury (uIRI), and it enhanced kidney function, reduced renal fibrosis while increasing microvessel density." (PMID 40682486, 2025). "Here, we also demonstrated that Rb1 exerts a renal protective effect in mice during the transition from AKI to CKD and can reduce renal fibrosis, the same as previously reported." (PMID 40682486, 2025). "Rb1 ameliorates EMT and renal fibrosis via inhibiting ROS production and activating the Bip/eIF2α/CHOP signalling pathway in HK2 cells." (PMID 40682486, 2025). "Notably, Rb1 has demonstrated efficacy in mitigating oxidative stress and inflammation in CKD models, while NADPH oxidase 4 (NOX4) knockout attenuates renal fibrosis by inhibiting fibroblast activation." (PMID 41508002, 2026). "In addition, Rb1, recognised as a natural modulator of autophagy, can prevent autophagy activation in the kidneys of UUO mice and alleviate renal fibrosis in UUO mice." (PMID 40682486, 2025).
sarcopenia (2 papers, 2021 to 2022). Progressive decline in muscle mass due to aging which results in decreased functional capacity of muscles. "Therefore, Rb1 could restore MuSC function to maintain skeletal muscle tissue homeostasis and serve as a pharmacological treatment for age-related sarcopenia." (PMID 36466088, 2022).
sebaceous carcinomas (2 papers, 2021 to 2025).
seminoma (2 papers, 2010 to 2021). A radiosensitive malignant germ cell tumor found in the testis (especially undescended), and extragonadal sites (anterior mediastinum and pineal gland). "In the subsequent studies, the same researcher group showed that LOH of the CDKN2A was found in two (6%) non-seminomas cases with a yolk sac tumor component, and LOH of the RB1 was also found in two (6%) non-seminomas with an embryonal carcinoma component." (PMID 34068019, 2021). "The analysis of intragenic polymorphic restriction marker of the RB1 gene showed that 34 (85%) of total TGCTs were heterozygous for this polymorphism; 15 (83%) seminomas and 19 (86%) nonseminomas." (PMID 22933911, 2010).
Sepsis (2 papers, 2022 to 2024). Sepsis is defined as life-threatening organ dysfunction caused by a dysregulated host response to infection. "Furthermore, we analyzed the downstream TFs targeted by LR pairs and found that different TFs, including SMAD3, RBPJ, and MAX, were targeted in sepsis-only patients, while FOS, STAT3, STAT2, and RB1 were targeted in sepsis-induced patients." (PMID 35222683, 2022). "Moreover, the downstream TFs targeted by the LR pairs in sepsis-induced ARDS are FOS, RB1, STAT2, and STAT3." (PMID 35222683, 2022).
T-cell acute lymphoblastic leukaemia (2 papers, 2016 to 2022). "Here, we identified that miR-590 and its predicted target gene RB1 are differentially expressed in T-cell acute lymphoblastic leukaemia (T-ALL)." (PMID 27036041, 2016).
teratoma (2 papers, 2015 to 2021). A non-seminomatous germ cell tumor characterized by the presence of various tissues which correspond to the different germinal layers (endoderm, mesoderm, and ectoderm). "Furthermore, teratoma formation was found to always be unilateral in Rb1 germ cell deficient mice." (PMID 26176933, 2015). "However, whether Rb1 deficiency in granulosa cells or germ cells leads to teratoma formation has been unclear." (PMID 26176933, 2015). "Mutational inactivation of the tumor suppressor retinoblastoma protein 1 (Rb1) gene has been detected in most types of human cancers, including human ovarian cancers and teratomas." (PMID 26176933, 2015). "The lack of evidence for more advanced stages of embryogenesis in ovaries of Rb1-cKO mice may simply reflect the relative rarity of teratoma formation or more rapid disorganization for the developmental background of the strain." (PMID 26176933, 2015). "Further, Rb1 was successfully deleted in teratoma tissues, and we found both Ddx4-cre transgene positive and negative teratomas, suggesting that teratomas arise from oocytes that have completed the first meiotic division." (PMID 26176933, 2015). "Multiple abnormal oocytes were evident in a given ovary of Rb1-cKO mice from PD 23 to 35; however, only rare cysts were present at the early stage of teratoma development, indicating not all activated oocytes became OTs." (PMID 26176933, 2015). "However, neither expression of Nanog nor Oct4 which are classical markers of pluripotent cells was detectable in Rb1-deficient ovaries at PD 14, 21, or 35, providing further evidence that persistent PGCs are not the source of teratomas in Rb1-cKO mice." (PMID 26176933, 2015). "Overall, these findings demonstrate that inactivation of Rb1 in oocytes does not increase the propensity for parthenogenetic activation in vitro, suggesting that impaired maintenance of meiotic arrest is not the driving force of teratoma formation." (PMID 26176933, 2015).
uterine cancer (2 papers, 2017 to 2020). Primary or metastatic malignant neoplasm involving the uterine corpus and/or the cervix. "Analogously, increased cell cycle activity was observed in the absence of RB1 loss, a putative mechanism of cell cycle dysregulation in uterine cancers." (PMID 33217970, 2020).
uterine corpus endometrial carcinoma (2 papers, 2020 to 2025). A endometrial carcinoma (disease) that involves the body of uterus. "The one exception to this relationship is in uterine corpus endometrial carcinoma (UCEC), where RB1 mutations and CDKN2A mutations are co-occurring." (PMID 32242058, 2020).
uterine sarcoma (2 papers, 2017 to 2020).
vulvar carcinoma (2 papers, 2016 to 2025). "Moreover, the two tumor components of the thyroid harbored identical mutations in KEAP1, RB1, and STK11, none of which were detected in the vulvar carcinoma." (PMID 40600748, 2025).
acromegaly (1 paper, 2021). Acromegaly is an acquired disorder related to excessive production of growth hormone (GH) and characterized by progressive somatic disfigurement (mainly involving the face and extremities) and systemic manifestations. "Additionally, whole genomic regions of seven genes (HMGA2, FGFR4, PTTG1, RB1, GNAS, AIP, GPR101) associated with acromegaly were added to the profiling target." (PMID 34400688, 2021).
acute kidney injury (1 paper, 2026). Sudden and sustained deterioration of the kidney function characterized by decreased glomerular filtration rate, increased serum creatinine or oliguria. "The consistent superiority of Rb1 over the canonical ferroptosis inhibitor Fer-1 positions this natural compound as a particularly promising therapeutic candidate for acute kidney injury intervention." (PMID 41508002, 2026).